LNPPS (lncRNA PDCD5 and p53 scaffold)
Gene: Long non-coding RNA gene on chromosome 5 (149,425,771 to 149,428,289, reverse strand). Ensembl gene ENSG00000275871.
Diseases named in the same sentence as LNPPS in open-access papers:
LNPPS is named in the same sentence as 1 disease in open-access papers, as found by Europe PMC text mining. Sharing a sentence is not in itself a finding about the gene and the disease. The quoted sentences say what the papers report.
tumour (1 paper, 2023). "qRT‐PCR results showed that only lncRNA AC131025.2 (Ensemble: ENST00000622374, renamed as LNPPS) was significantly downregulated in BC tissues compared with paired non‐tumour tissues, consistent with the RNA‐seq data." (PMID 36578176, 2023). "Our present study identified LNPPS as a novel tumour suppressor with the ability to inhibit BC growth in vivo." (PMID 36578176, 2023). "Similar to the findings in vitro, overexpression of LNPPS suppressed the growth of subcutaneous tumours, whereas LNPPS knockdown increased the tumour volume and weight." (PMID 36578176, 2023). "IHC staining data of the subcutaneous tumours demonstrated that the proportion of Ki‐67‐positive cells was decreased by overexpression of LNPPS." (PMID 36578176, 2023).